EGFR (epidermal growth factor receptor)
Diseases named in the same sentence as EGFR in open-access papers (continued):
Sharing a sentence is not in itself a finding about the gene and the disease.
glioma (continued). "Following the reclassification of gliomas according to the 2016 WHO classification, we investigated the role of TERT promoter mutations, EGFR amplification, PTEN deletion and MGMT promoter methylation in molecular glioma subgroups." (PMID 31623593, 2019). "We further performed receiver operating characteristic (ROC) analysis to evaluate the discriminatory efficacy of EGFR+ EVs in distinguishing glioma patients and control individuals." (PMID 31410219, 2019). "We also found that neoplastic cell clusters of gliomas express significantly higher level of EGFR than that of healthy cell clusters." (PMID 31118022, 2019). "EGFRamp tumors exhibit erlotinib resistance and respond to a combination of MET and EGFR inhibitors, which was demonstrated through the use of intracranial xenograft glioma models." (PMID 31221203, 2019). "In human glioma, simultaneous activation of multiple RTKs, including EGFR, VEGFR, FGFR and PDGFR, can constitutively activate key oncogenic downstream cascades, including PI3K-Akt-mTOR and Erk-MAPK signaling." (PMID 31794427, 2019). "The expression level of EGFR was analyzed in the serum EVs from glioma patients with different grades diagnosed on the basis of the World Health Organization (WHO) classification." (PMID 31410219, 2019). "The results of present study demonstrated that in glioma cells Ninj2 co-immunoprecipitated with multiple RTKs (including EGFR, PDGFRβ and FGFR), required for downstream Akt and Erk activation." (PMID 31794427, 2019). "Some evidence also showed that the expression of EGFR has some relationship with glioma patient prognosis, although this conclusion has been contradicted by other studies, and the prognostic value of EGFR for glioma has not been demonstrated to date 39-41." (PMID 31410219, 2019). "Multiple growth factor receptors including MET and EGFR are known to be overexpressed in aggressive gliomas." (PMID 31595389, 2019). "Lapatinib is a combined EGFR/Her2 TKI that targets two glioma cell survival pathways, which was shown to reduce the PDT light dose threshold in multiple cell lines in vitro." (PMID 31847378, 2019). "Conversely, miR-566 inhibition slows the proliferation of glioma cells and sensitizes them to anti-EGFR agents." (PMID 31757094, 2019). "The ITH in high-grade glioma was elucidated in a scRNA-seq study through profiling gene expression of single cells in EGFR amplified and PDGFRA amplified tumors." (PMID 31586689, 2019). "Then, we also analyzed the impact of TERT promoter mutations, PTEN deletion, EGFR amplification and MGMT promoter methylation in diagnosis, prognosis and response to therapy in glioma molecular subgroup." (PMID 31623593, 2019). "Both the immortalized and primary glioma cells with GOLPH3 over‐expression hold higher EGFR protein levels on the cell membrane and exhibited higher sensitivity to gefitinib." (PMID 31094020, 2019). "We evaluated the ability of EGFR+ EVs to differentiate high-grade and low-grade glioma patients and checked the correlation between EGFR in EVs and the ki-67 labeling index (LI) in the tumor tissue." (PMID 31410219, 2019). "Examined by EGFR immunofluorescence, we found that, either in the U251 or in the primary cultured glioma cells, the EGFR protein levels increased and accumulated at the cell membrane after GOLPH3 over‐expression." (PMID 31094020, 2019). "The U251 and U87 glioma cells with GOLPH3 over‐expression exhibited higher EGFR level on the plasma membrane." (PMID 31094020, 2019). "To date, most studies evaluated the prognostic value of EGFR amplification using only the histological diagnosis, instead of the molecular subgroups of gliomas." (PMID 31623593, 2019). "Human EJ28Luc urothelial carcinoma and LN18 glioma cells were treated with lethal activity concentrations of a 213Bi-anti-EGFR immunoconjugate." (PMID 31165773, 2019).
glioma (continued). "We evaluated the diagnostic efficacy of serum EVs for glioma patients and found that EGFR+ EVs were able to diagnose glioma patients with high sensitivity and specificity (AUC 0.900, 95% CI 0.8064 ~ 0.9936, P <0.0001)." (PMID 31410219, 2019). "The overexpression of miR-566 in human glioma cell lines activates the epidermal growth factor receptor (EGFR) pathway, through direct targeting of VHL." (PMID 31757094, 2019). "For instance, IDH1 silencing specifically increases erlotinib (an EGFR, epidermal growth factor receptor, inhibitor) efficacy in patient-derived glioma-initiating cells (GICs) carrying EGFR amplification." (PMID 31010244, 2019). "MDGI has been previously shown to affect EGFR trafficking, inhibition of which can induce glioma cell apoptosis." (PMID 31068339, 2019). "Indolent glioma cells can acquire epidermal growth factor receptor variant III (EGFRvIII), a tumor-specific truncated form of EGFR, from microvesicles released by aggressive glioma cells harboring this variant." (PMID 30925930, 2019). "Similar to the results found in U251 cells, the protein level/intensity of EGFR increased in GOLPH3 over‐expression GBM2 primary glioma cells and mainly located at cell membrane." (PMID 31094020, 2019). "Dacomitinib inhibited cell viability and proliferation of epidermal growth factor receptor (EGFR)-amplified glioma." (PMID 30782784, 2019). "EGFR806-CAR T cells only infiltrated EGFR-positive teratomas if the they were activated by a glioma at a different site in the same animal." (PMID 31903167, 2019). "Flow cytometry results indicated that the expression level of EGFR in EVs was significantly higher in the glioma patients compared to the healthy donors and was dramatically decreased one week after surgery (****P < 0.0001, one-way ANOVA)." (PMID 31410219, 2019). "The expression of GOLPH3 and EGFR in glioma cells was detected by immunofluorescence and immunoblotting." (PMID 31094020, 2019). "Epidermal growth factor receptor (EGFR) is associated with the progression of a wide range of cancers including breast, glioma, lung, and liver cancer." (PMID 31546749, 2019). "Enrichment of MYC on the EGFR/EGFRvIII promoter region can notably facilitate the malignant phenotypes of glioma cells." (PMID 30795814, 2019). "To define the clinical relevance of our finding that Fyn phosphorylates 6PGD Y481 upon EGFR activation, we performed immunohistochemistry (IHC) analyses in 117 glioma specimens using anti-6PGD pY481 and anti-Fyn antibodies." (PMID 30824700, 2019). "In the human glioma tissues (“T1/T2/T3”, derived three primary glioma patients), Ninj2-immunoprecipitation with EGFR, PDGFRβ and FGFR was detected as well." (PMID 31794427, 2019). "We previously showed that the downregulation of the EGFR-MEK-ERK signaling pathway mediated the induction of senescence in berberine-treated glioma cells." (PMID 30910997, 2019). "We previously reported that Golgi phosphoprotein 3 (GOLPH3) promotes glioma progression by inhibiting EGFR endocytosis and degradation, leading to EGFR accumulation and PI3K‐AKT pathway over‐activation." (PMID 31094020, 2019). "The intravenously injected conjugate enabled the specific imaging of EGFR expression and demonstrated therapeutic efficacy in subcutaneous glioma xenografts." (PMID 30669481, 2019). "Epidermal growth factor receptor (EGFR) has been reported to be dysregulated in most cancers, including gliomas and its functions are closely linked to initiating tumor metastasis and a very poor prognosis." (PMID 30587839, 2018).
glioma (continued). "In 2017, it was determined that an up-regulated expression of CRNDE induces EGFR (Epidermal Growth Factor Receptor) activation, resulting in poor survival in glioma patients and apoptosis inhibition through increased Bcl2/Bax (BCL2 Associated X) ratio." (PMID 30583549, 2018). "The fact that EGFR functions one of the most vital factors to promote gliomas has attracted many investigations of EGFR inhibitors, aiming to promote apoptosis of cancer cells, or to increase tumor sensitivity to possible adjuvant therapies." (PMID 30016965, 2018). "Recently, the miRNA-146b, which shows sequence similarity with miR-146a has been shown to inhibit glioma growth in vitro through modulation of its target EGFR." (PMID 29861845, 2018). "Gefitinib has also been proved to inhibit invasion (dependent of EGFR amplification) and angiogenesis (depending on EGFR status) in glioma tumors implanted in mouse brain slices." (PMID 30486451, 2018). "preferentially binds glioma cells with EGFR amplification, is internalized and releases a potent antimicrotubule agent, monomethyl auristatin F (MMAF)." (PMID 30271342, 2018). "Collectively our observations highlight pathways critical to glioma susceptibility, notably neural development and NAD metabolism, as well as EGFR-AKT signalling." (PMID 29460007, 2018). "Upregulated genes, such as EGFR and MYO1C, are associated with glioma cell proliferation and migration, whereas downregulated genes such as MMP11 and SREBF1 are related to cell adhesion and lipid metabolism (bottom)." (PMID 29587824, 2018). "Recently, CRNDE was shown to promote glioma malignancy through activation of epidermal growth factor receptor (EGFR) signaling and preventing miR-136-5p-mediated downregulation of Bcl-2 and Wnt2." (PMID 30217088, 2018). "EGFR gene amplification is one of the most frequent genetic alterations observed in glioma, and EGFR expression generally correlates with WHO grade in gliomas." (PMID 29487691, 2018). "Encouragingly, our in vitro and proof‐of‐concept in vivo studies clearly highlight the potential of eradicating EGFR+ve glioma cells using ZEGFR:03115–IR700DX‐targeted PIT." (PMID 29313975, 2018). "Amplifications and rearrangements of EGFR are highly indicative of high-grade gliomas, with a worse prognosis than estimated from just histopathologic grading." (PMID 30016965, 2018). "MiR-34a functions as a tumor suppressor via modulating epidermal growth factor receptor (EGFR) or PD-L1 translation directly in glioma." (PMID 30687086, 2018). "The p38 pathway was suggested to affect survival, cell cycle state and differentiation status of glioma CSCs via regulating EGFR trafficking." (PMID 30510501, 2018). "We treated glioma cells with an irreversible dual EGFR/ErbB2 inhibitor (afatinib) to evaluate the effects of the EGFR and ErbB2 pathways on DSE-regulated malignant phenotypes." (PMID 29864158, 2018). "As an example, since different glioma cell lines are characterized by a variable overexpression of EGFR, GNPs were functionalized with a monoclonal antibody anti-EGFR (Panitumumab) promoting their internalization by tumor cells." (PMID 29867737, 2018). "The direct involvement of mTORC2 in GBM biology clearly emerged in a Drosophila glioma model obtained by hyperactivating the epidermal growth factor receptor (EGFR), RAS and PI3K." (PMID 30662577, 2018). "This study helped confirm that pediatric high-grade gliomas rely less on EGFR amplification, which adult grade IV gliomas often possess, and instead rely more on platelet-derived growth factor receptor (PDGFR) amplifications." (PMID 30340362, 2018).
glioma (continued). "Linkage of boron-containing liposomes to the MoAb cetuximab (C225 or ErbituxTM) resulted in specific in vitro molecular targeting of EGFR expressing F98EGFR glioma cells." (PMID 29914561, 2018). "Bradykinin can stimulate the B2 receptor and epidermal growth factor receptor (EGFR) signaling pathways to enhance the gliomas invasion, and then to promote angiogenesis through the increased VEGF expression." (PMID 30068373, 2018). "Glioma-associated DEGs CD244, IL21, RET, TGFA were up-regulated and AQP9, IGFBP2, EGFR, SOX9 were down-regulated specifically in the rat." (PMID 29352201, 2018). "The Fe3O4@Au-C225 composite targeted MNPs synthesized in our previous study can target EGFR in glioma specifically, and the magnetic property shows super paramagnetic, and a high degree of biocompatibility." (PMID 29652919, 2018). "Recently, the expression and functional significance of EGFR in glioma-initiating cells has been explored." (PMID 30279357, 2018). "Recently, the molecular pathology study of glioma showed that the overexpression of EGFR is always present in patients with malignant glioma." (PMID 29652919, 2018). "HOXA-AS2 regulates malignant glioma behaviors and vasculogenic mimicry formation via the MiR-373/EGFR Axis." (PMID 30376874, 2018). "EGF/EGFR inhibition was driven by the large role played in glioma genesis and in mechanisms involved in tumor growth, such as reduced apoptosis, proliferation, invasion or angiog1enesis." (PMID 29329222, 2018). "A well-studied target for peptide vaccines is the epidermal growth factor receptor (EGFR), a receptor tyrosine kinase that is highly expressed in high grade gliomas compared to normal brain tissue." (PMID 30568917, 2018). "Studies have demonstrated that Akt also induces Notch1 expression in a mouse glioma model and EGFR, conversely, seems to be under the transcriptional control of Notch signaling." (PMID 28629170, 2017). "Taken together, our data demonstrate that BTK is required for EGFR-induced NF-κB activation in glioma cells." (PMID 28946903, 2017). "Twenty-two compounds of the 95 tested exhibited considerable potency against GBM cells in vitro, and were screened initially using tumorigenic Ink4a/arf EGFR-VIII mouse glioma stem cells because these cells express high levels of OLIG2." (PMID 26517684, 2017). "Our results suggest that BTK is a novel critical mediator of EGFR-induced NF-κB activation in glioma cells." (PMID 28946903, 2017). "Detailed descriptions of the EGFR signaling networks and the deregulated signaling of EGFRvIII in glioma can be found in excellent reviews." (PMID 28629170, 2017). "MAPK signaling is one of the main EGFR downstream pathways that are known to be critical for glioma tumourigenesis." (PMID 29069756, 2017). "U373 glioma cells that expressed a highly oncogenic form of epidermal growth factor receptor (EGFR), called EGFRvIII, had the ability to transmit this protein to non-EGFRvIII expressing cells via EVs." (PMID 28848498, 2017). "EGFR is the only common gene detected by all five tools, suggesting that EGFR plays a pivotal role in the tumorigenesis of glioma." (PMID 29046615, 2017). "EGFR gene is amplified in 40% of the malignant gliomas and about one half of these glioma cells have a mutant form of the receptor (EGFRvIII) that lacks the ligand-binding domain, thus becoming constitutively active." (PMID 29261132, 2017). "A key message of the present study is that inhibition of PC-PLC by D609 also downmodulates CXCR4, EGFR expression and downstream signaling pathways responsible for cell growth and cell motility in our experimental glioma cells." (PMID 28423060, 2017).
glioma (continued). "EGFR signalling plays a significant role in the pathogenesis of glioma, and therefore, inhibition of EGFR-mediated oncogenic signalling leads to apoptosis." (PMID 29029435, 2017). "A previous study uncovered that miR‐30e enhanced glioma cell invasion through EGFR stabilization by directly targeting CBL‐B23." (PMID 28653805, 2017). "As radiation treatment is the principal modality for treating glioma, we tested the combinational effect of EGFR inhibition and radiation on cell proliferation and clonogenic survival." (PMID 29069805, 2017). "A positive correlation between EGFR expression and migration ability has been previously reported in glioma cell lines and in neuronal stem cells therefore our results would further support the role of EGFR in cell motility." (PMID 28587680, 2017). "Our analyses of clinical gliomas reveal a close correlation between co-expression of TRIM24/p-EGFR, TRIM24/H3K23ac and TRIM24/p-STAT3 with poor prognoses in GBM patients." (PMID 29129908, 2017). "Overexpression of epidermal growth factor receptor (EGFR) is observed in many different cancers, including gliomas, sarcomas, and head and neck cancers." (PMID 29088889, 2017). "In this study a new contrast agent consisting of a fluorescently labeled Affibody molecule that binds to the epidermal growth factor receptor (EGFR) was examined for uptake in orthotopic glioma tumors to assess the contrast available to guide surgery." (PMID 27379987, 2017). "Establishing robust imaging biomarkers is of great significance for predicting EGFR-defined subtypes of glioma, to help in clinical decision making." (PMID 29097933, 2017). "So far, only one study reported the participation of another PHD family member, PHD3, in EGFR stability in glioma." (PMID 28038470, 2017). "MiR-146b has been found to silence EGFR and to reduce invasion and motility of glioma cells; however, expression of this miRNA is lost in the majority of glioma tumours." (PMID 28538671, 2017). "More importantly, BTK inhibition effectively blocked both baseline and EGFR-induced activation of NF-κB pathway mediating glioma cell proliferation and survival." (PMID 28946903, 2017). "Located downstream of EGFR signaling, we have revealed the important role of mTOR complex 2 (mTORC2) in glioma pathogenesis through chemoresistance and metabolic reprogramming." (PMID 29207533, 2017). "Amplification and gain-of-function mutations of epidermal growth factor receptor (EGFR) are the most common genetic alteration in the brain cancers, with a frequency of approximately 40% in glioma." (PMID 28830458, 2017). "Taken together, our results provide strong evidence for the potential use of cRGD-siRNA to target EGFR in glioma as an anticancer therapeutic." (PMID 28181832, 2017). "The newly established roles of TRIM24 and H3K23ac in tumorigenesis provide a strong rationale for targeting them to treat glioma patients with high EGFR and STAT3 signaling activity." (PMID 29129908, 2017). "The expression of IL-13Rα2 and EGFR in glioma cell lines used in our studies was first determined (respectively)." (PMID 29203859, 2017). "A phase 2 trial is actually ongoing (NCT02800486) and addresses the specific question of the combination of EGFR inhibitor cetuximab with stereotactic HFRT for the treatment of previously irradiated recurrent high grade glioma." (PMID 28754127, 2017). "Expression of EGR-1 gene in glioma cells is induced by overexpression of EGFR and PDGFR genes, thus suggesting EGR-1 as a connection of growth factor stimulation with gene expression changes." (PMID 29138748, 2017). "ARAF takes part of the RAS-MAPK pathway being activated by EGF/EGFR activation and supporting invasiveness of gliomas." (PMID 27613830, 2017).